NPIPB3 (nuclear pore complex interacting protein family member B3)
Synonyms: KIAA0220; formerly NPIPL3
Tractability: Antibody: UniProt predicts a signal peptide or a membrane-spanning region.
Gene: Protein-coding gene on chromosome 16 (21,402,237 to 21,448,567, reverse strand). Ensembl gene ENSG00000169246.
Subcellular location: Membrane
Subcellular location (Human Protein Atlas): Nucleoplasm
Pathways (Reactome):
Disease: SARS-CoV-1 activates/modulates innate immune responses
Gene Ontology:
Molecular function: protein binding
Cellular component: nuclear envelope; membrane
Genetic constraint (gnomAD): Loss-of-function variants: 0 observed, 0.59 expected, observed/expected ratio (o/e) 0, 90% interval 0 to 1.82. That is too few expected variants to judge how well the gene tolerates losing a copy. Missense variants: 0 observed, 28.65 expected, observed/expected ratio (o/e) 0, 90% interval 0 to 0.1. Synonymous variants: 1 observed, 10.47 expected, observed/expected ratio (o/e) 0.0956, 90% interval 0.033 to 0.45.
Homologues: Paralogues in human: NPIPB5 (100% identical), NPIPB4 (99% identical), NPIPB12 (99% identical), NPIPB13 (99% identical), NPIPB11 (88% identical), NPIPB15 (35% identical), NPIPB8 (35% identical), NPIPB9 (35% identical), NPIPB2 (34% identical), NPIPB7 (34% identical), NPIPB6 (32% identical), NPIPA6 (31% identical), and 7 more.
Diseases named in the same sentence as NPIPB3 in open-access papers:
NPIPB3 is named in the same sentence as 2 diseases in open-access papers, as found by Europe PMC text mining. Sharing a sentence is not in itself a finding about the gene and the disease.
NPIPB3 shares sentences with these, for which no sentence is quoted: CNS tumor (1 paper); tumor (1).